YEATS2 (YEATS domain containing 2)
Diseases named in the same sentence as YEATS2 in open-access papers (continued):
Sharing a sentence is not in itself a finding about the gene and the disease.
sarcoma (1 paper, 2021). A usually aggressive malignant neoplasm of the soft tissue or bone. "Via Kaplan-Meier analysis, we showed that increased expression of YEATS2 or ZZZ3 predicted a poorer prognosis across different histological types of sarcoma, suggesting the ATAC complex may be a key oncogenic driver in multiple sarcomas in addition to EHE." (PMID 33913810, 2021). "Overall survival curves as a function of YEATS2 (I) and ZZZ3 RNA expression (J) across different histological types of sarcoma utilizing RNA-Seq expression data for The Cancer Genome Atlas (TCGA)." (PMID 33913810, 2021). "To determine if expression of YEATS2 and ZZZ3 could be prognostically important in sarcomas other than EHE, we utilized RNA-Seq expression data from sarcoma clinical samples from The Cancer Genome Atlas (TCGA) database." (PMID 33913810, 2021). "In addition, RNA expression profiling data show that expression of YEATS2 and ZZZ3 have prognostic significance in sarcoma clinical samples across various histological types, suggesting that the ATAC complex might represent a key oncogenic driver in other sarcomas." (PMID 33913810, 2021).
cancer (14 papers, 2017 to 2025). A tumor composed of atypical neoplastic, often pleomorphic cells that invade other tissues. "We found that YEATS2, that encodes for a histone reader protein, was the only gene that was significantly upregulated in cancer as compared to normal tissues." (PMID 40810390, 2025). "For instance, in cancer, dysregulation or mutations of YEATS2 can lead to aberrant gene expression and chromatin modifications, contributing to the oncogenic processes." (PMID 38186679, 2023). "Given its capacity to recognize modified histones, the YEATS2 protein exerts epigenetic control over the transcriptional program crucial for driving cancer progression." (PMID 40216980, 2025). "This involvement in cancer progression underscores the importance of YEATS2 as a potential biomarker for cancer prognosis and a target for therapeutic intervention." (PMID 38186679, 2023). "YEATS2 acts as a distinct reader of histone crotonylation and serves as a novel oncogene in various cancers." (PMID 37853482, 2023). "Pan-cancer analyses from the single-cell level indicated that RBBP7 and YEATS2 were both associated with multiple cancer functional statuses, re-confirming the vital roles of these genes in the initiation and progression of malignant cancers." (PMID 36503492, 2022). "Afterward, YEATS2 expression was detected in a series of HNSCC cancer cells, including FaDu, Detroit562, UPCI-SCC-090 and CAL-27." (PMID 34587874, 2021). "As exhibited in, the expression of YEATS2 was relative abundant in Detroit562 and FaDu compared with other cancer cells (p < 0.05)." (PMID 34587874, 2021). "Through bioinformatic analysis, we found YEATS2 was abnormally high expression in HNSCC tissues compared the non-cancer tissues." (PMID 34587874, 2021). "To determine how YEATS2 regulates cancer cell growth and survival, we performed RNA-seq analysis in YEATS2 KD cells to identify the genes regulated by YEATS2 genome-wide." (PMID 29057918, 2017). "As per the evidence provided by us, it could be proposed that the surge in GCDH in YEATS2-high cancer cells affects the chromatin by increasing the pool of crotonyl-CoA inside nucleus, which acts as a substrate for histone-modifying enzymes." (PMID 40810390, 2025). "While exploring the relationship of YEATS2 with cancer cell metabolism, we found that YEATS2 is co-expressed with crotonyl-CoA producing GCDH (glutaryl-CoA dehydrogenase) in HNC, and the downregulation of either of these two genes led to a decrease in H3K27cr levels in HNC cells." (PMID 40810390, 2025). "The YEATS2 gene exhibits pronounced amplification across diverse human cancer types." (PMID 40216980, 2025). "It has been reported that YEATS2 may function as a methylation driver gene in cancer patients with smoking history." (PMID 36980736, 2023). "Depletion of YEATS2-reduced cancer cell growth, survival and transformation activity." (PMID 29057918, 2017). "To determine whether YEATS2 plays a role in human cancers, we first examined YEATS2 gene expression status across cancers in The Cancer Genome Atlas database via The cBioPortal for Cancer Genomics." (PMID 29057918, 2017). "Whether YEATS2 O-GlcNAcylation plays a role in these cancer types warrants further investigation." (PMID 40541806, 2025). "YEATS2 has also been found to activate the TAK1/NF-κB and PI3K/AKT signaling pathways, influencing cancer cell survival." (PMID 37853482, 2023). "Here, we show that the YEATS2 gene is highly amplified in human non-small cell lung cancer (NSCLC) and is required for cancer cell growth and survival." (PMID 29057918, 2017). "To explore whether YEATS2 overexpression was related to HNSCC development, we firstly detected YEATS2 expression in human oral epithelial cell line HIOEC and different cancer cell lines, including FaDu, Detroit562, UPCI-SCC-090 and CAL-27." (PMID 34587874, 2021).
tumor (11 papers, 2017 to 2025). "Up to now, there are few reports on the association between EIF5A2, HGD, HS6ST1, PLS1, PTHLH, and YEATS2 methylation modification and tumor." (PMID 34796198, 2021). "In addition, the study found that IGF2BP2 and its co-expressed genes (HMGA2, PHLDB2, and YEATS2) are all associated with a variety of TICs in OSCC tumor samples." (PMID 35129592, 2022). "Single-cell RNA sequencing analyses indicated that RBBP7 and YEATS2 were both associated with the tumor immune response, and the prognosis signature could predict the immunotherapeutic response in two cohorts receiving immunotherapy (P < 0.05; P < 0.01)." (PMID 36503492, 2022). "In conclusion, we have proved that the expression and copy number variation of YEATS2 were related to the tumor differentiation and the prognosis of patients in ESCC." (PMID 40040791, 2025). "We generated stable H1299 cells that overproduce YEATS2-WT or -T604A and then carried out mouse xenograft experiments, and the tumor size and weight were monitored." (PMID 40541806, 2025). "A 3D invasion assay was also performed to check the ability of tumor spheres to invade a collagen matrix in YEATS2-knockdown and -overexpressed conditions." (PMID 40810390, 2025). "Analysis of paired samples in TCGA database also showed that YEATS2 was upregulated in HCC tissues compared with adjacent tumor tissues." (PMID 36980736, 2023). "In summary, YEATS2 can affect tumor progression by regulating MMP7 expression through the PI3K/AKT signaling pathway." (PMID 36980736, 2023). "We found that overexpression of YEATS2 promoted tumor cell proliferation, migration, and invasion through the PI3K/AKT signaling pathway and regulation of extracellular matrix." (PMID 36980736, 2023). "We found that overexpression of YEATS2 promoted the process of tumor proliferation, migration, and invasion." (PMID 36980736, 2023). "Here, the present study disclosed that YEATS2 was highly expressed on neutrophils in the tumor microenvironment, which provided a novel cut-in point to elucidate the biological functions of YEATS2 in tumorigenesis." (PMID 36503492, 2022). "Collectedly, our present work revealed that YEATS2 depletion possessed tumor inhibitory function in HNSCC cells, which expression was regulated by miR-378a-5p." (PMID 34587874, 2021). "In order to investigate the function of YEATS2 expression on the tumor characteristics of HNSCC cells, we used YEATS2 specific siRNA to disturb YEATS2 expression in Detroit562 and FaDu cells." (PMID 34587874, 2021). "Moreover, the expression of YEATS2 was upregulated in higher tumor grades (grades 2–4) as compared to grade 1 tumors." (PMID 40810390, 2025). "Besides, by constructing subcutaneous tumorigenesis model and lung metastatic tumor model in nude mice, we have found that stable YEATS2 knockdown significantly inhibited proliferation and migration of KYSE150 in vivo." (PMID 40040791, 2025). "In vivo and in vitro experiments supported the tumor promoting effect of YEATS2." (PMID 40040791, 2025). "Our findings reveal a novel mechanism by which YEATS2 regulates tumor progression." (PMID 36980736, 2023). "Furthermore, in in vitro soft agar colony formation assays and in vivo xenograft assays, depletion of YEATS2-suppressed tumor growth." (PMID 29057918, 2017). "Importantly, WT YEATS2, but not the H3 acetylation-binding deficient mutants, restored the transformation capability of the YEATS2 KD H1299 cells in vitro and tumor growth in mice." (PMID 29057918, 2017). "(E) Representative IHC images showing the levels of ECHS1, GCDH, YEATS2, H3K27cr, and Twist1 in HNC normal vs. tumor tissue samples (n=8) (Scale bar, 100 μm)." (PMID 40810390, 2025). "ECHS1 expression was notably reduced in tumor tissues, whereas GCDH, YEATS2, H3K27cr, and Twist1 exhibited increased staining intensity in tumor sections compared to the adjacent normal tissues." (PMID 40810390, 2025).
tumor (continued). "To explore tumor-promoting epigenetic factors in HNC, we analyzed large gene expression dataset and narrowed down our search to YEATS2 (YEATS-domain containing protein 2)." (PMID 40810390, 2025). "Our study showed that overexpression of YEATS2 significantly increased the expression of p-PI3K, p-Akt, suggesting that YEATS2 can regulate tumor progression through the PI3K/AKT signaling pathway." (PMID 36980736, 2023). "In addition, the anti-tumor effect of miR-378a-5p could be attributed to targeting YEATS2." (PMID 34587874, 2021). "Additionally, we performed IHC to evaluate the levels of ECHS1, GCDH, YEATS2, H3K27cr, and Twist1 in HNC tumor and their matched normal tissue sections." (PMID 40810390, 2025). "In addition, CASP8 was found to regulate YEATS2 in HCC, highlighting a potential pathway in tumor progression." (PMID 38186679, 2023). "Interestingly, we observed that YEATS2 was primarily expressed on neutrophils (P < 0.001) and RBBP7 was predominantly expressed in macrophages (P < 0.001), implying both of these genes are involved in tumor immune response of early-stage LUAD." (PMID 36503492, 2022).
head and neck tumor (1 paper, 2025). "In our study, we identified YEATS2 as an important epigenetic regulator that plays an oncogenic role in head and neck tumor progression." (PMID 40810390, 2025).
YEATS2 also shares sentences with these, for which no sentence is quoted: acute myeloid leukemia (1 paper); adult familial myoclonic epilepsies (1); breast carcinoma (1); Friedreich ataxia (1); Fuchs endothelial corneal dystrophy (1); glioma (1); leukemia (1); lung squamous cell carcinoma (1); ovarian serous cystadenocarcinoma (1); pancreatic adenocarcinoma (1); prostate carcinoma (1); spinocerebellar ataxia type 37 (1); temporal lobe epilepsy (1).